FH (fumarate hydratase)
Diseases named in the same sentence as FH in open-access papers (continued):
Sharing a sentence is not in itself a finding about the gene and the disease.
Renal cyst (17 papers, 2011 to 2025). A fluid filled sac in the kidney. "Mutation or loss of fumarate hydratase (FH) can transform cells to become oncogenic and forms tumours leading to renal cysts and cancer." (PMID 35382567, 2022). "HLRCC is caused by a mutation of fumarate hydratase (FH), the Krebs cycle enzyme, functioning as a tumor suppressor gene and the inactivation of FH initiates formation of multiple renal cysts." (PMID 27100828, 2016). "In line with our findings in FH-deficient cell lines, many of the epithelial cells facing the lumen of the renal cysts showed an intense staining for p21." (PMID 25613188, 2015). "Bardella and coworkers applied this concept to FH-associated neoplasia and demonstrated the presence of 2SC in murine FH-deficient renal cysts and in a retrospective series of 16 HLRCC tumors." (PMID 26380143, 2015). "For instance, activation of the Hif1α mediated hypoxic response takes place upon loss of SDH in MEFs, of FH in MEFs and renal cysts, and upon neuronal expression of the Idh1R132H mutation." (PMID 25126540, 2014). "We undertook a proteomic-based screen in cells and renal cysts from Fh1 (murine FH)-deficient mice and identified 94 protein succination targets." (PMID 23499446, 2013). "Remarkably, transgenic re-expression of cytosolic FH ameliorated both renal cyst development and urea cycle defects associated with renal-specific FH1 deletion in mice." (PMID 23643539, 2013). "We demonstrate that re-expression of cytosolic FH in FH1-deficient mice is critical for the suppression of renal cyst development and restoration of defects in the arginine biosynthesis pathway." (PMID 23643539, 2013). "Striking parallels exist with the Krebs cycle enzyme fumarate hydratase (FH), a tumor suppressor, whose mutation is associated with the development of leiomyomata, renal cysts, and tumors." (PMID 22866264, 2012). "The Krebs cycle enzyme fumarate hydratase (FH) is a human tumor suppressor whose inactivation is associated with the development of leiomyomata, renal cysts, and tumors." (PMID 22014577, 2011). "Inactivation of the tumor suppressor gene encoding fumarate hydratase (FH) causes activation of hypoxia signaling, and it has been proposed that this plays a causal role in renal cyst and tumor development." (PMID 22014577, 2011). "To assess the role of HIF activation in FH-associated renal cystic disease, we determined if parallel inactivation of Hif-1α or Hif-2α would ameliorate the hyperplastic renal cystic phenotype in mice with renal tubule specific inactivation of Fh1." (PMID 22014577, 2011). "Therefore, we recommend to intensify surveillance if renal cysts are detected in FH mutation carriers, using shorter intervals between scans." (PMID 31792767, 2020). "The pathogenesis of renal cyst formation in FH-deficient patients has been partially elucidated." (PMID 26380143, 2015). "Likewise, an accumulation of fumarate modified selected cysteine residues in Keap1 and abrogated the function of Keap1 to promote Nrf2 proteolysis and it led to an increase in the renal cyst formation of fumarate hydratase (FH)-deficient mice." (PMID 25014534, 2014). "HIF is strongly upregulated, both in HLRCC-associated human pRCC and in the hyperplastic renal cysts that develop in mice following targeted inactivation of Fh1 (the murine homolog of FH), and studies of gene expression patterns in these tissues have revealed strong signatures of HIF activation." (PMID 22014577, 2011). "Affected individuals also develop renal cysts, a phenotype that is recapitulated in FH1 (murine FH)-deficient mice." (PMID 23643539, 2013). "To investigate the role of extramitochondrial FH in renal cyst development, we have undertaken high-resolution mass-spectrometry-based metabolomic analyses of FH-deficient cells, renal cysts, and tumors." (PMID 23643539, 2013). "In this study, Pollard and colleagues demonstrate the importance of cytosolic fumarate hydratase (FH) in renal cyst development in mice." (PMID 23643539, 2013).
Renal cyst (continued). "Nevertheless, Fh1-loss-associated renal cyst formation has been shown to be HIF-independent, suggesting that these transcription factors, despite being crucial regulators of the response to FH loss are dispensable for transformation, at least in this model." (PMID 37689804, 2023). "Fumarate hydratase (FH) is a TCA cycle enzyme that catalyzes the hydration of fumarate to malate and is considered a tumor suppressor; the inactivation of FH is associated with leiomyomata, renal cysts, and tumors." (PMID 33080927, 2020). "In summary, we have utilized a murine model of early HLRCC to demonstrate that renal cyst development is independent of mitochondrial FH activity." (PMID 23643539, 2013). "However, the actual limitation of the genetic murine models with mutations in SDH, FH, and IDH enzymes generated to date is that they do not develop tumors in any case, being the renal cyst formation of kidney-specific FH mutant be the most reliable phenotype of uncontrolled cell proliferation." (PMID 25126540, 2014). "Analyses of mice defective in both FH and HIF signaling reveal that inactivation of Hif-1α but not Hif-2α actually exacerbates renal cyst development." (PMID 22014577, 2011).
fumarate hydratase deficiency (16 papers, 2008 to 2025). "Fumarate hydratase deficiency (FMRD) is a rare autosomal recessive disorder of organic acid metabolism caused by a genetic variant in the FH gene, locating on chromosome 1q42.1." (PMID 40217354, 2024). "P5 presented a homozygous variant in the FH gene c.1358T>C (p.Leu453Pro), which was previously reported in a Moroccan female with severe fumarase deficiency associated with significant encephalopathy." (PMID 38283147, 2023). "Fumarase deficiency is an autosomal recessive condition characterized by severe neurologic abnormalities due to homozygous mutations in the fumarate hydratase (FH) gene." (PMID 37663422, 2023). "Homozygous or compound heterozygous FH mutations result in fumarase deficiency, a rare autosomal recessive disorder characterized by severe neurologic and developmental deficits." (PMID 37663422, 2023). "The objective of our study was to characterize the infertility diagnoses, treatments, and outcomes in women presenting to a fertility center who were found to be carriers of fumarase deficiency based on the presence of heterozygous FH mutations." (PMID 37663422, 2023). "The fumarase deficiency is a monogenic disorder due to the impairment of the fumarate hydratase enzyme, caused by a mutation in the fumarate hydratase gene, which encodes the enzyme." (PMID 26376088, 2015). "The panel includes a gene called fumarate hydratase (FH), as if both of a person’s two copies of the FH gene are not working properly it causes a severe syndrome (fumarate hydratase deficiency) which includes muscle weakness." (PMID 37339848, 2024). "Additionally, six patients had FH P/LP variants (p.Gln376Pro (n = 3), p.His402Tyr (n = 2), p.Gly397Arg (n = 1)) that have been reported in homozygous and compound heterozygous patients with fumarate hydratase deficiency, but have not, to our knowledge, been reported in patients with HLRCC." (PMID 35971132, 2022).
leiomyosarcoma (15 papers, 2002 to 2026). An uncommon, aggressive malignant smooth muscle neoplasm, usually occurring in post-menopausal women. "The biological significance of FH deficiency in uterine leiomyosarcoma (uLMS), including its relationship with germline FH mutations and its impact on patient outcomes, is still under study." (PMID 40002168, 2025). "Association of leiomyosarcoma with germline FH mutations has been reported, although the risk appears to be lower than previously estimated." (PMID 41162745, 2025). "FH heterozygous mutations predispose to FH gene tumor susceptibility syndrome, characterized by cutaneous smooth muscle tumors, uterine smooth muscle tumors (leiomyosarcomas), or renal tumors." (PMID 38285218, 2024). "Leiomyosarcomas also occur in association with FH mutations but appear to be rare in FH mutation carriers although a few cases, predominantly of Finnish origin, have been described." (PMID 18366737, 2008). "Germline mutations in the fumarate hydratase gene at 1q43 predispose to dominantly inherited skin and uterine leiomyomata and leiomyosarcomas." (PMID 12177782, 2002). "Of the LM/leiomyosarcoma (LMS) tumors with an unknown FH mutation status, 1 uterine LM and 1 cutaneous LM (from a patient with suspected HLRCC), and 2 LMS tumors were positive for 2SC." (PMID 26472283, 2015). "As our understanding of FH deficiency and its role in tumorigenesis evolves, future research is needed to better define the long-term oncological risks associated with FH-deficient tumors, particularly regarding their potential to undergo transformation into leiomyosarcoma." (PMID 40002168, 2025). "So far, no study has proven the linkage between FH loss of expression and leiomyosarcoma transformation." (PMID 40002168, 2025). "Although most ULMS do not share common genetic drivers with ULs, MED12 hotspot mutations, HMGA2 overexpression and FH inactivation have been shown to occur in some ULMS cases, suggesting that leiomyosarcomas may originate from Uls." (PMID 40016412, 2025). "None of the 26 leiomyosarcomas harboured somatic mutations in fumarate hydratase." (PMID 12177782, 2002). "Although in the leiomyosarcomas LOH was common, this reflected extensive loss of chromosome 1q rather than being limited to the vicinity of FH." (PMID 12177782, 2002).
prostate carcinoma (14 papers, 2014 to 2025). A carcinoma that arises from epithelial cells of the prostate gland. "Our findings are therefore consistent with a number of previous reports on the association of mtDNA mutations with the aggressiveness of a number of tumor types, including prostate cancer and fumarate hydratase-deficient renal cancer." (PMID 34337412, 2021). "This is especially interesting given that somatic mutations in fumarate hydratase have been reported in a small subset of prostate cancer patients." (PMID 32103057, 2020). "In contrast to the tumor-promoting role of aconitase in prostate cancer, the inhibition of this enzyme has been observed in fumarate hydratase (FH)-deficient cancer cell lines." (PMID 25057353, 2014). "Most of the TCA enzymes are upregulated during the first metabolic shift in prostate cancer, and then either stay upregulated (CS, FH) or are downregulated (e.g. ACO2, OGDH, and SUCLG1) during the second shift." (PMID 29563510, 2018). "Previously, several studies have been reported that FH is frequently mutated in renal cancer, ELOVL2 is upregulated in hepatocellular cancer, and ACADL is associated with prostate cancer progression." (PMID 29262542, 2017). "The three-fold decrease in IDH2 expression normalised the TCA cycle in prostate cancer cells, and the 4.3-fold increase in FH expression inhibited fumarate build-up in prostate cancer cells and deactivated the angiogenic factor hypoxia-inducible factor 1-alpha." (PMID 36771106, 2023). "We show here that high levels of nuclear ARRB1 in prostate cancer cells result in downregulation of FH and SDHA expression, although this effect is likely to be an indirect consequence as our genomics analysis did not identify any ARRB1-binding sites in the promoter regions of these two genes." (PMID 24837709, 2014). "In the present study, we have clearly revealed that FABP5 activated expression of metabolic genes (ATP5B, LCHAD, ACO2, FH and MFN2) via a novel signaling pathway in an ERRα (estrogen-related receptor α)-dependent manner in prostate cancer cell lines." (PMID 30167092, 2018). "Although FH and MDH2 activities were comparable among prostate cancer and benign cell lines at the basal condition, interestingly, Alternol enhanced their activities in prostate cancer cells but not in BPH1 cells." (PMID 33224877, 2020).
acute myeloid leukemia (11 papers, 2013 to 2023). Acute myeloid leukemia (AML) is a group of neoplasms arising from precursor cells committed to the myeloid cell-line differentiation. "Manipulation of the citric acid cycle is of particular interest, given recent studies that have linked mutations in several enzymes of this cycle, including IDH1/2, SDH, and fumarate hydratase (FH), with the pathogenesis of acute myeloid leukemia." (PMID 23887041, 2013). "This includes IDH1/2 in gliomas and acute myeloid leukaemia (AML), SDH in PGLs and FH in HLRCC due to the production of oncometabolites, D-2-HG, succinate and fumarate." (PMID 35382567, 2022).
clear cell renal cell carcinoma (11 papers, 2011 to 2025). "Nomenclature modifications were observed in the context of papillary and clear cell renal cancer: HLRCC nomenclature was modified to FH-deficient RCC, and renal medullary cancer has been revised to SMARCB1-deficient RCC." (PMID 38765391, 2024). "It has been shown that 15% of people with the FH gene variant will develop clear-cell renal carcinoma." (PMID 39336594, 2024). "The FH gene change leads to a rare aggressive subtype of clear-cell renal carcinoma caused by an inherited or sporadic loss-of-function variant of the FH gene." (PMID 39336594, 2024). "It has been previously shown that inhibiting heme synthesis is selectively lethal to renal clear cell carcinoma with fumarate hydratase mutation." (PMID 32103057, 2020). "In another study in clear cell renal cancer, a mutation in FH led to the accumulation of HIF-2α, a promotor renal carcinogenesis." (PMID 31817761, 2019). "However, a recent report has linked FH to the development of clear cell renal cancer in a patient with a germline mutation of FH." (PMID 21695080, 2011). "In addition to VHL, pathogenic or potentially pathogenic variants in the MET, FLCN, TSC1, TSC2, FH, and SDH genes also contribute to the development of clear-cell renal carcinoma." (PMID 39336594, 2024). "FH mutations have not been identified in sporadic clear cell renal cancer." (PMID 21695080, 2011). "Therefore, we investigated the role of FH in sporadic clear cell renal cancer." (PMID 21695080, 2011). "Finally, we found that FH is downregulated in a set of clear cell renal cell carcinoma, and FH expression is positively correlated to EMT markers, confirming the link between FH and EMT in vivo in hereditary and sporadic tumours." (PMID 27886164, 2017).
Hypercholesterolemia (11 papers, 2017 to 2024). An increased concentration of cholesterol in the blood. "This study emphasizes the importance of genetic testing for patients with familial hypercholesterolemia and the importance of knowing if we are dealing with a FH variant carrier when approaching the management of these patients." (PMID 39459389, 2024). "A total of 22 of 45 carriers (48.9%) of an FH variant met clinical criteria for severe hypercholesterolemia (estimated untreated LDL cholesterol ≥190 mg/dL) compared with 951 of 9648 noncarriers (9.9%)." (PMID 35294538, 2022). "ClinVar database of global familial hypercholesterolemia-associated DNA variants ClinGen FH Variant Curation Expert Panel." (PMID 34709306, 2021). "Few data exits on the future lipid-trajectory in children with a pathogenic FH mutation, but one report showed that 11 of 25 children with an FH mutation and LDL-C below 3.5 mmol/L developed hypercholesterolemia during 3.8 years of follow up." (PMID 31809987, 2020). "The score is being administered to FH mutation-negative patients with hypercholesterolaemia in order to provide them with an explanation for their hypercholesterolaemia (i.e., a polygenic cause or not)." (PMID 35432461, 2022). "Patients who did not have a FH mutation in our study may still have polygenic forms of hypercholesterolemia caused by multiple genetic factors resulting in elevated LDL-C levels and risk of early development of atherosclerotic cardiovascular disease (ASCVDs)." (PMID 39131706, 2024). "The other possible explanation for the lack of a mutation in the three known FH genes could be that the hypercholesterolaemia is due to a mutation in an undiscovered gene(s)." (PMID 29213121, 2017). "Our study shows that ABCG5/8 could be underestimated in pediatric patients with hypercholesterolemia and NGS has an advantage in diagnosing sitosterolemia or carriers of ABCG5/8 gene comparing to gene panels of FH." (PMID 36991406, 2023). "Therefore, this study was designed to confirm the molecular defects of hypercholesterolemia in pediatric patients using whole-exome sequencing (WES) rather than gene panels of FH, basing on a single-center group of children and adolescents." (PMID 36991406, 2023).
lung carcinoma (10 papers, 2007 to 2025). "Studies have shown that FH inhibits the metastasis of non–small cell lung cancer by suppressing the AMP-activated protein kinase signal pathway." (PMID 41380966, 2025). "And our experimental results also showed that FH level was significantly upregulated in lung cancer cell lines, including lung adenocarcinoma cell line A549." (PMID 34737838, 2021). "In the primary culture of human lung tissues, we observed that FH levels were also high in two out of three conditioned media of lung cancer cells compared with that of primary normal lung cells." (PMID 30987235, 2019). "The immunohistochemical stain showed a high level of FH expression in human lung cancer tissues compared with normal lung tissues." (PMID 30987235, 2019). "FH is also secreted in several cancers, such as nonsmall cell lung cancer, ovarian cancer, and colon cancer." (PMID 30987235, 2019). "The high level of FH may provide the lung cancer cells a means to escape immune surveillance and maintain their stability." (PMID 30987235, 2019). "To investigate whether the higher FH expression level in lung cancer cell lines are translated to primary cells, we performed immunohistochemistry staining on human lung tissues and Western blot analysis on the primary culture of human lung tissues." (PMID 30987235, 2019). "Moreover, siRNA mediated knockdown of FH has been shown to increase HIF-1α levels in A549 lung carcinoma cells which express VHL." (PMID 21695080, 2011). "In this study, the authors found that TGFβ-induced FH-CSL interactions and cell growth arrest were significantly inhibited in lung cancer cells, which were reversed by PAK4 inhibition." (PMID 31435524, 2019). "PAK4, highly expressed in lung cancers, counteracts the anti-proliferative effect induced by TGFβ/FH/CSL cascade by phosphorylating FH on Ser46, an event that—contrarily to the phosphorylation on Thr90—impairs the interaction between FH and CSL, favoring tumor proliferation and metastasis." (PMID 34065551, 2021). "Although there are no stimuli, lung cancer cell lines constitutively express high levels of FH." (PMID 30987235, 2019).